RNU7-4P (RNA, U7 small nuclear 4 pseudogene)
Synonyms: U7.4; RNU7-132P
Gene: Small nuclear RNA gene on chromosome 12 (68,911,921 to 68,911,982, forward strand). Ensembl gene ENSG00000252770.
Homologues: Orthologues: macaque U7 (92% identical). Paralogues in human: RNU7-3P (94% identical), RNU7-11P (90% identical), RNU7-14P (90% identical), RNU7-8P (90% identical), RNU7-1 (89% identical), RNU7-25P (89% identical), RNU7-26P (89% identical), RNU7-2P (89% identical), RNU7-13P (87% identical), RNU7-27P (87% identical), RNU7-47P (87% identical), RNU7-49P (87% identical), and 142 more.